IL33 (interleukin 33)
Diseases named in the same sentence as IL33 in open-access papers (continued):
Sharing a sentence is not in itself a finding about the gene and the disease.
hepatocellular carcinoma (continued). "In this study, the role of interleukins IL-33, IL-17, and IL-25 in HCV patients and progression of disease from chronicity to hepatocellular carcinoma will be characterized in order to use them as biomarkers of disease progression." (PMID 35056005, 2022). "In the present study, the serum levels of IL-33, IL-17 and IL-25 were determined in patients with chronic hepatitis C (CHC) and hepatocellular carcinoma (HCC) and compared to healthy controls (C)." (PMID 35056005, 2022). "Current studies highlight the role of the IL-33, IL-17, and IL-25 in the pathogenesis of HCV and its progression to hepatic carcinoma." (PMID 35056005, 2022). "For example, local IL-33 production in a mouse model of hepatocellular carcinoma was shown to enhance CD4+ and CD8+ anti-tumor activity, warranting a re-evaluation of the use of IL-33-neutralizing drugs in tumor models." (PMID 30949175, 2019). "Current results indicate a significant role of IL-33 in liver inflammation and fibrosis progress in CHC, whereas IL-17 and IL-25 may be used as biomarkers for the development of hepatocellular carcinoma." (PMID 35056005, 2022). "The relation between IL-33 and sST2 serum levels and the survival of patients suffering from liver cirrhosis (LC) and hepatocellular carcinoma (HCC) has not been determined yet." (PMID 30483263, 2018). "The components of IL-33 signaling axis (IL-33/ST2/IL-1RAcP) are increased in human and mouse fibrotic livers but not, interestingly, in human hepatocellular carcinoma." (PMID 27882334, 2016).
Myocardial fibrosis (31 papers, 2015 to 2026). "Compared to wild-type mice, targeted ST2-disrupted mice exhibited more severe left ventricular hypertrophy and myocardial fibrosis, as well as the loss of the IL-33 function." (PMID 40295953, 2025). "IL-33 is a cytokine produced by cardiac fibroblasts that can cause cardioprotective effects against hypertrophic remodeling and myocardial fibrosis by antagonizing angiotensin-II signaling and promoting anti-apoptotic factors, respectively." (PMID 37833616, 2024). "At the cardiac level, the ST2L/IL-33 interaction initiates a complex cardioprotective biochemical cascade, which prevents cardiomyocyte hypertrophy, apoptosis, and myocardial fibrosis, thereby improving cardiac function." (PMID 37998526, 2023). "IL-33 is the functional ligand of ST2l, and the IL-33/ST2l signaling pathway has been shown plays a role in anti-myocardial fibrosis and cardiomyocyte hypertrophy." (PMID 38274310, 2023). "IL-33 is considered as a myocardial protective factor, which can inhibit cardiomyocyte apoptosis, reduce myocardial fibrosis and inflammatory response, and improve survival and function of ischemic myocardium." (PMID 35004889, 2021). "When cardiomyocytes stretch, sST2 is released, neutralizing its ligand IL-33, which is a key component in preventing myocardial fibrosis and hypertrophy." (PMID 34368254, 2021). "The experiments showed that IL33-MSCs decreased T cells proliferation, and enhanced the polarization of M1 phenotype to M2 phenotype, and the myocardial fibrosis, inflammation, and cardiac function recovered better with IL33-MSCs." (PMID 35096808, 2021). "ST2L/IL-33 signaling also activates cell survival-promoting signals, resulting in several cardioprotective effects, such as inhibition of myocardial fibrosis and cardiomyocyte hypertrophy." (PMID 34404341, 2021). "The interaction of ST2L with its ligand, IL-33, is cardioprotective, reducing myocardial fibrosis and hypertrophy." (PMID 31992225, 2020). "Previous studies have revealed a strong correlation between interleukin-33 (IL-33) and myocardial fibrosis." (PMID 33376501, 2020). "IL-33 exerts antihypertrophic effects in cultured cardiomyocytes that are antagonized by administration of sST2, and reduces myocardial fibrosis and cardiomyocyte hypertrophy in response to pressure overload in mice." (PMID 26390433, 2015). "Moreover, YAP/TAZ factors regulate the promoter activity of pro-fibrotic cytokine interleukin-33 (IL-33) and contribute to its secretion by cardiac fibroblasts, thereby promoting myocardial fibrosis." (PMID 41191311, 2026). "SST2 may bind free IL-33, substantially reducing the amount of IL-33 accessible for ST2L binding, attenuating the cardioprotective effect of IL-33, and ultimately contributing to myocardial fibrosis." (PMID 36204571, 2022). "Previous studies have revealed a strong correlation between IL-33 and myocardial fibrosis." (PMID 33376501, 2020). "In myocardial fibrosis, YAP can act as a downstream signal of Wnt and TGF‐β and contributes to the secretion of the profibrotic cytokine IL‐33 in cardiac fibroblasts, thereby promoting myocardial fibrosis." (PMID 37576865, 2023). "IL-33 binds to a receptor complex composed of ST2L and IL-1 receptor accessory protein, which prevents cardiomyocyte hypertrophy, apoptosis, and myocardial fibrosis, thereby improving cardiac function." (PMID 36204571, 2022). "Interaction between IL-33 and IL1RL1 in experimental models results in the reduction of myocardial fibrosis and apoptosis and the improvement of cardiac function." (PMID 31924244, 2020). "Of note, IL-33 exerts a cardioprotective role via ST2 signaling, while soluble ST2 has been demonstrated as a marker of myocardial fibrosis." (PMID 30405626, 2018).
Myocardial fibrosis (continued). "ST2 competes with a membrane bound receptor (ST2 ligand, or ST2L) for interleukin-33 (IL-33) binding, inhibiting the effects induced by the ST2L/IL-33 interaction so that excessive sST2 may contribute to myocardial fibrosis and ventricular remodeling." (PMID 37998526, 2023). "This study investigated the effects of miR-487b activation of IL-33 through inhibition of the IL-33/ST2 signaling pathway in CHF, and we found that miR-487b suppresses the apoptosis, the inflammatory reaction of myocarditis, and myocardial fibrosis." (PMID 28881679, 2017). "Moreover, IL-33/IL1RL1 signaling could activate TGF-β-mediated fibroblast activation and epithelial-mesenchymal transition in the myocardium, promoting extracellular matrix (ECM) production, thereby driving myocardial fibrosis and structural remodeling characteristic of HCM." (PMID 40599543, 2025).
periodontitis (31 papers, 2014 to 2026). An acute or chronic inflammatory process that affects the tissues that surround and support the teeth. "Although the frequency of periodontitis was similar in all groups, higher IL-6 (p = 0.004), IL-1β (p = 0.002), and IL-33 (p = 0.006) levels were associated with poor periodontal status." (PMID 40008732, 2025). "In the context of periodontitis, IL‐33 has been shown to mitigate alveolar bone loss by modulating the local immune environment and promoting tissue repair." (PMID 41399014, 2025). "In the pathogenesis of periodontitis, the cellular release of IL-33 can exert a damage-associated molecular pattern-like (DAMP) function." (PMID 36947565, 2023). "One SNV of the IL33 gene also showed a statistically significant inverse association with moderate periodontitis." (PMID 36947565, 2023). "In periodontitis, there is a greater expression of pro-inflammatory cytokines, such as the IL-33 produced by MCs, associated with the pathogenesis of periodontal disease." (PMID 36362030, 2022). "This study provided evidence that P. gingivalis-induced IL-33 expression was associated with the pathogenesis of periodontitis." (PMID 30205617, 2018). "This sustains the reliability of this experimental model to mimic the alveolar bone loss related to periodontitis in human and so, to investigate the potent role of IL-33 in the inflammatory cascade associated to the CP pathogenesis." (PMID 27992569, 2016). "Some studies have shown a positive association between elevated levels of IL-33 in periodontal tissue and periodontitis." (PMID 27403039, 2016). "Some previous studies have reported both protective and pathogenic roles of IL-33 in periodontitis." (PMID 41374934, 2025). "Both Il1rl1- and Il33-deficient mice exhibit exacerbated bone loss in the acute phase of periodontitis, along with macrophage polarization towards a classically activated phenotype and increased neutrophil infiltration, indicating a protective role of the IL-33/ST2 axis in acute inflammation." (PMID 38548743, 2024). "OSA may increase the risk of developing periodontitis due to increase of IL-1β and IL-6 in saliva and IL-6, IL-17A and IL-33 in GCF that share the activation of the osteoclastogenesis." (PMID 36967976, 2023). "These cytokines may be considered biomarkers of both conditions, emphasizing the association between IL-33 and stage IV periodontitis." (PMID 36967976, 2023). "These exploratory findings of genetic variants in IL-33/ST2 axis support the concept that the different tissue responses among individuals with periodontitis may be modulated by the host’s genetics, influencing the physiopathology of the disease." (PMID 36947565, 2023). "Finally, an inverse association (OR <1) between the SNVs of the IL33 gene and moderate periodontitis was also observed with the SNV rs2066362 (A allele)." (PMID 36947565, 2023). "Interestingly, however, induction of periodontitis in AMPK KO mice further increased IL-33 mRNA expression and also caused significant increases in expression levels of both IL-5 and IL-13." (PMID 28861078, 2017). "To further analyze whether IL-33 can be involved in the increased alveolar bone loss associated to periodontitis, we used mouse gingival explants treated with IL-33 for 24 hours." (PMID 27992569, 2016). "In contrast, cytokines with antiatherogenic potential, such as IL-5, IL-10, IL-13, IL-19, IL-27, IL-33, IL-37, and TGF-β, are rarely mentioned in the context of periodontitis, except IL-33." (PMID 39062000, 2024). "IL-33 released from IL-33ECs is highly expressed after induction of periodontitis, but tends to be stable after the acute phase, suggesting that its function as an alarmin is not important." (PMID 38548743, 2024). "We then examined the expression of IL-33 in periodontal tissues after the induction of periodontitis." (PMID 38548743, 2024).
periodontitis (continued). "Although further direct evidence (e.g., induction of periodontitis in mST2-specific knockout mice) is needed, our findings shed some light on the involvement of the IL-33/ST2 axis in the pathogenesis of experimental periodontitis." (PMID 38548743, 2024). "At the cellular level, IL-33 is overexpressed in gingival epithelial cells in chronic periodontitis and in a murine experimental periodontitis model with elevated expression of RANKL." (PMID 38098978, 2023). "Among candidate genes, some of such studies have suggested the influence of the Interleukin-33 gene in the pathogenesis of periodontitis." (PMID 36947565, 2023). "Further research is necessary to support the role of IL-33 in the physiopathology of OSA in patients with periodontitis." (PMID 36967976, 2023). "Further, expression of IL-33 was upregulated in gingival samples from patients with chronic periodontitis and in rats with induced periodontitis and was accompanied by increased RANKL expression in gingival epithelial cells." (PMID 36902030, 2023). "Both the IL-33 gene and IL1RL1 gene (ST2 gene) have been implicated in the immune response in periodontitis, as well as in chronic disease of the airways, such as asthma." (PMID 36947565, 2023). "There was a significant positive correlation between IL-33 in saliva and stage IV periodontitis in G4(P-OSA) (rs = 0.531)." (PMID 36967976, 2023). "This study investigated associations between single nucleotide variants (SNVs) in the IL33 gene and in the IL1RL1 (ST2) gene with periodontitis." (PMID 36947565, 2023). "In periodontitis, the expression of IL-33 in gingival epithelial and connective tissue cells acts as an alarmin of tissue damage for the immune system, inducing RANKL expression and triggering the recruitment of RANKL-expressing B and T cells." (PMID 36967976, 2023). "This study aims to compare the salivary and gingival crevicular fluid (GCF) concentrations of five cytokines: IL-1β, IL-6, IL-17A, IL-33, and Tumor Necrosis Factor-alpha (TNF-α) in patients with OSA and their association with periodontitis." (PMID 36967976, 2023). "For example, the levels of IL-33 and granulocyte colony-stimulating factor (G-CSF), encoded by the CSF3 gene, are increased in mice with experimentally induced periodontitis and in gingival epithelial cells from periodontitis patients." (PMID 36776856, 2023). "In patients with periodontitis, IL-33 is highly expressed both at the site of onset and in a periodontitis model infected with Porphyromonas gingivalis, and IL-33 exacerbates alveolar bone loss and aggravates the disease in a RANKL-dependent manner." (PMID 36291105, 2022). "IL-1 and IL-33 are pleiotropic cytokines from members of the IL-1 family that mediate the inflammation of the MCs and contribute to many key features of periodontitis and other inflammatory disorders." (PMID 36362030, 2022). "IL-1 and IL-33 are pleiotropic cytokines from members of the IL-1 family, which mediate inflammation of MCs and contribute to many key features of periodontitis and other inflammatory disorders." (PMID 36362030, 2022). "Nevertheless, IL-33 has been implicated in the activation of RANKL expression in T and B cells during periodontitis." (PMID 34594237, 2021). "Expression of IL-33 increased in patients with chronic periodontitis as compared to healthy patients." (PMID 30205617, 2018). "IL-33 expression was assessed by immunohistochemistry in gingival tissues from patients with chronic periodontitis." (PMID 30205617, 2018). "Changes in the oral microbiota were linked to increased local inflammation, as demonstrated by higher concentrations of IL-6, IL-17, and IL-33 in SLE patients with periodontitis." (PMID 28320468, 2017). "While periodontitis primarily increased expression of IL-33, knockdown of AMPK markedly increased expression of each cytokine in periodontal tissues of mice with ligature-induced periodontitis." (PMID 28861078, 2017).
periodontitis (continued). "Induction of periodontitis in wild mice markedly increased expression of IL-33 but expression levels of IL-5 and IL-13 resembling those of sham-operated groups." (PMID 28861078, 2017). "Nonetheless, our data show upregulation of IL-33 in both the murine model of periodontitis and the human condition." (PMID 28861078, 2017). "In light of the more marked expansion of the pool of ILC2s in periodontitis, we also explored mRNA expression of ILC2s-related cytokines, namely IL-5 and IL-13; we also determined expression of IL-33 since it is a pivotal regulator of function of ILC2s." (PMID 28861078, 2017). "Consistently higher levels of IL-6, IL-17, and IL-33 were detected in SLE patients with periodontitis." (PMID 28320468, 2017). "Subsequently, we showed that human periodontitis is associated with increases in each ILCs subtype with the effect more marked for ILC2s and that mRNA expressions for IL-33 and IL-5 are markedly greater for sites affected by periodontitis than healthy sites." (PMID 28861078, 2017). "There was a significant increase in inflammatory cytokines IL-6, IL-17, and IL-33 in saliva of SLE patients with periodontitis compared to control group with periodontitis." (PMID 28320468, 2017). "In a rat model of ligature induced-periodontitis, IL-33 expression was upregulated concomitantly to RANK-L." (PMID 27992569, 2016). "We showed in this study that IL-33 is overexpressed in gingival epithelial cells in human affected by CP as in a murine model of experimental periodontitis (EP)." (PMID 27992569, 2016). "Interleukin-33 was expressed in the cytoplasm of inflamed gingival epithelium from patients with chronic periodontitis, but scarcely in that from healthy individuals." (PMID 27058037, 2016). "The present study found that IL-33 expression was increased in gingival epithelia from patients with chronic periodontitis." (PMID 27058037, 2016). "We detected IL-33 in inflamed gingival epithelium from patients with chronic periodontitis, and found that P. gingivalis increased IL-33 expression in the cytoplasm of human gingival epithelial cells in vitro." (PMID 27058037, 2016). "A second work would be the study of the effects of IL-33 in circulating monocytes and bone marrow from periodontitis-induced animals, which is similar to the previously proposed work." (PMID 24692848, 2014). "In the paper that compared cytokine levels for 54 periodontitis patients and 40 healthy controls, cytokines IL‐1β, IL‐4, IL‐6, IL‐10, IL‐17A, IL‐17F, IL‐21, IL‐22, IL‐23, IL‐25, IL‐31, IL‐33, IFN‐γ, sCD40L and TNF‐α were measured in saliva and serum at baseline, 3, 6 and 12 months after treatment." (PMID 41580300, 2026). "Optimization of the tissue collection method improved the quality of the RNA-seq analysis of the isolated samples, resulting in the discovery of the importance of the IL-33/ST2 axis in periodontitis after confirming the significant upregulation of Il1rl1 in the PRT." (PMID 38548743, 2024). "Thus, our findings highlight the hidden role of the peri-root tissue and simultaneously advance our understanding of the etiology of periodontitis via implicating the IL-33/ST2 axis." (PMID 38548743, 2024). "The function of the IL-33/ST2 axis in the pathogenesis of periodontitis remains unclear and requires further systematic investigation." (PMID 38548743, 2024). "Thus, our results provide in vivo evidence for the critical role of the PRT and the unique character of the IL-33/ST2 axis in the pathogenetic process of periodontitis." (PMID 38548743, 2024). "Accordingly, the present study aimed to investigate associations between single nucleotide variants (SNVs) in the IL-33 gene and in the ST2 gene with periodontitis and between these SNVs and the relative amount of A. actinomycetemcomitans in the subgingival biofilm." (PMID 36947565, 2023).